ERMN (ermin)
Description:
Plays a role in cytoskeletal rearrangements during the late wrapping and/or compaction phases of myelinogenesis as well as in maintenance and stability of myelin sheath in the adult. May play an important role in late-stage oligodendroglia maturation, myelin/Ranvier node formation during CNS development, and in the maintenance and plasticity of related structures in the mature CNS (By similarity).
Synonyms: JN; KIAA1189
Tractability: Antibody: the Human Protein Atlas places it where antibodies can reach.
Gene: Protein-coding gene on chromosome 2 (157,318,626 to 157,327,713, reverse strand). Ensembl gene ENSG00000136541.
Subcellular location: Cytoplasm, cytoskeleton
Subcellular location (Human Protein Atlas): Plasma membrane; Cytosol
Gene Ontology:
Molecular function: protein binding; actin filament binding; actin binding
Biological process: actin filament organization; regulation of cell projection organization; regulation of cell shape; morphogenesis of a branching structure
Cellular component: cell cortex; cytoplasm; extracellular exosome; internode region of axon; paranode region of axon; filopodium; myelin sheath; neuronal cell body; cytoskeleton
Genetic constraint (gnomAD): Loss-of-function variants: 13 observed, 21.46 expected, observed/expected ratio (o/e) 0.61, 90% interval 0.39 to 0.96. The upper end of that interval is the gene's LOEUF score, 0.96, which puts it in group 4 of 6, group 1 being the genes least tolerant of losing a copy. Missense variants: 308 observed, 312.25 expected, observed/expected ratio (o/e) 0.99, 90% interval 0.9 to 1.08. Synonymous variants: 105 observed, 107.81 expected, observed/expected ratio (o/e) 0.97, 90% interval 0.83 to 1.14.
Homologues: Orthologues: chimpanzee ERMN (99% identical), macaque ERMN (94% identical), dog ERMN (77% identical), rabbit ERMN (76% identical), pig ERMN (73% identical), rat Ermn (62% identical), mouse Ermn (60% identical), zebrafish msna (27% identical), zebrafish msnb (25% identical), Drosophila melanogaster Moe (23% identical). Paralogues in human: RDX (27% identical), MSN (26% identical), EZR (25% identical), NF2 (21% identical), FRMD4B (19% identical), FRMD4A (15% identical).
Diseases named in the same sentence as ERMN in open-access papers:
ERMN is named in the same sentence as 21 diseases in open-access papers, as found by Europe PMC text mining. Sharing a sentence is not in itself a finding about the gene and the disease. The quoted sentences say what the papers report.
multiple sclerosis (3 papers, 2020 to 2021). A progressive autoimmune disorder affecting the central nervous system resulting in demyelination. "Transcripts encoding adenosin A2a receptor (Adora2a) and ermin (Ermn) have been associated with neurodegeneration, multiple sclerosis and epileptic seizures." (PMID 32742258, 2020). "ERMN expression is dysregulated in a series of nervous system diseases, including multiple sclerosis and neurodegenerative disorders." (PMID 34516348, 2021). "ERMIN has not previously been associated with multiple sclerosis and the regulation of this protein should thus be investigated further during phases of de- and remyelination in patients." (PMID 33785790, 2021).
COVID-19 (2 papers, 2025). A disease caused by infection with severe acute respiratory syndrome coronavirus 2. "Consequently, the research pinpointed four key genes, MBP, CYP4B1, ERMN, and SLC26A7, which hold clinical relevance and exhibit potential significance in the pathophysiology of COVID-19 induced depression." (PMID 40918512, 2025).
epilepsy (2 papers, 2021 to 2024). A brain disorder characterized by episodes of abnormally increased neuronal discharge resulting in transient episodes of sensory or motor neurological dysfunction, or psychic dysfunction. "Expression of ERMN is lower in patients with epilepsy which suggests its role in the epileptogenic process." (PMID 34349621, 2021).
autism (1 paper, 2021). Persistent deficits in social interaction and communication and interaction as well as a markedly restricted repertoire of activity and interest as well as repetitive patterns of behavior. "Remarkably, ERMN is located inside the AUTS5 locus boundaries, which has been repeatedly shown to be linked with autism, language impairment, and IQ." (PMID 34349621, 2021).
developmental delay (1 paper, 2021). "Besides, deletions including ERMN were reported in impaired communication and developmental delay patients." (PMID 34349621, 2021).
hepatoblastoma (1 paper, 2016). Hepatoblastoma (HB) is a malignant hepatic tumor and is the most common pediatric liver cancer. "Cytogenetic data of hepatoblastoma have revealed that up-regulation of GALNT5, DAPL1, ERMN, SCN1A and SCN3A plays a major role in the development and progression of the disease." (PMID 27322213, 2016). "However, the post-translational modifications regulated by GalNAcT5 in hepatoblastoma cells remain undefined, as the mechanism of action of DAPL1, ERMN, GALNT5, SCN1A and SCN3A genes." (PMID 27322213, 2016).
multiple myeloma (1 paper, 2022). "Moreover, we found that YY1 mutation could affect the expression changes of certain genes in some cancers; for example, in multiple myeloma, YY1 mutation could affect the expressions of ERMN, DUSP8, PRG2, BMF, and RNASE2 genes." (PMID 35791393, 2022).
prostate adenocarcinoma (1 paper, 2021). "Similarly, a previous study demonstrated that ERMN was highly expressed in the microenvironment of prostate adenocarcinoma and had the potential to regulate the tumor immune response." (PMID 34516348, 2021).
relapsing-remitting MS (1 paper, 2021). "Besides, a study suggested that reduced ERMN expression in the leukocytes could cause demyelination in patients with relapsing-remitting MS." (PMID 34349621, 2021).
tumor (3 papers, 2021). "There are few studies on ERM-like protein (ERMN) in tumours." (PMID 34294834, 2021). "The results indicated that FABP4, ERMN, and CHST11 were overexpressed in CRC tumor tissues compared with normal tissues." (PMID 34294834, 2021).
ERMN also shares sentences with these, for which no sentence is quoted: infection (2 papers); alcohol dependence (1); autism spectrum disorder (1); cancer (1); depression (1); Infertility (1); nervous system diseases (1); neuromuscular disease (1); Parkinsonism (1); schizophrenia (1); uterine cancer (1).